TG (thyroglobulin)
Diseases named in the same sentence as TG in open-access papers (continued):
Sharing a sentence is not in itself a finding about the gene and the disease.
Graves ophthalmopathy (3 papers, 2014 to 2020). An autoimmune disorder of the EYE, occurring in patients with Graves disease. "Higher thyroglobulin antibody levels were found in patients with Graves’ ophthalmopathy than in patients without this ophthalmopathy." (PMID 32631402, 2020).
hypercoagulability (3 papers, 2020 to 2025). "The inclusion criteria of this prospective study included inherited and acquired thrombophilia, compound heterozygous polymorphisms, and positive anti-nuclear and anti-thyroglobulin antibodies, which were strong indications for steroid hormone and anticoagulant drugs." (PMID 35351031, 2022). "In addition, exercise induced hypercoagulability as observed by significant changes in all measured markers, including TAT, D-Dimer, aPTT, PF4 and Beta-TG." (PMID 32537688, 2020).
hypophosphatemia (3 papers, 2014 to 2024). Lower than normal levels of phosphates in the circulating blood. "Laboratory analysis revealed high ALP levels (1,080 mg/ml), with severe hypophosphatemia (1.4 mg/ml), high thyroglobulin (Tg) levels (65.2 mg/ml), normal calcium levels (8.7 mg/dl) and normal parathyroid hormone levels (58.7 mg/ml)." (PMID 24959220, 2014).
malaria (3 papers, 2017 to 2024). Malaria is a serious and sometimes fatal disease caused by a parasite that commonly infects a certain type of mosquito which feeds on humans. "Thyroglobulin mean concentration levels were high in healthy children, 20.91 μg/L (SD 2.49), compared to the malaria-infected children, with a mean difference of 0.91 μg/L, but it was not significant." (PMID 39728830, 2024).
Poorly differentiated thyroid carcinoma (3 papers, 2004 to 2025). "This pattern also differs from that seen in those tumours referred to as poorly differentiated (e.g. Insular carcinoma), which although capable of producing thyroglobulin behave in a clinically aggressive manner." (PMID 15150580, 2004). "Poorly differentiated thyroid carcinoma (PDTC) is a tumor type with intermediate features and somewhat better prognosis; PDTC often shows some residual thyroid architecture or thyroglobulin production, whereas ATC loses thyroid differentiation entirely." (PMID 41425129, 2025). "Poorly differentiated thyroid carcinoma (PDTC) exhibits diffuse nuclear positivity for thyroid transcription factor 1 (TTF1) and focal positivity for thyroglobulin." (PMID 27213120, 2016).
renal dysfunction (3 papers, 2016 to 2024). "The proportion of patients with hepatic dysfunction, renal dysfunction, high triglyceride and total cholesterol levels, and positive thyroid peroxidase or thyroglobulin antibodies was similar between the two groups." (PMID 34512539, 2021).
struma ovarii (3 papers, 2011 to 2018). An ovarian mature teratoma characterized by the presence of aberrant thyroid tissue. "Thyroidectomy followed by a diagnostic staging radioiodine scan and a stimulated thyroglobulin level should be considered in patients with malignant struma ovarii for guiding therapeutic I-131 administration as metastatic risk is difficult to predict based on histopathologic examination." (PMID 29946481, 2018). "Postoperative I-131 total body scanning and serum thyroglobulin monitoring is recommended for the management and follow-up of patients with malignant struma ovarii for residue, recurrence or metastasis." (PMID 22152685, 2011). "Increased thyroglobulin levels can support a diagnosis of struma ovarii if antithyroglobulin antibodies are absent." (PMID 22152685, 2011).
adrenal gland tumor (2 papers, 2013 to 2018). "In our case, melan-A and inhibin were positive, but thyroglobulin and TTF-1 were negative, in the patient’s adrenal gland tumor." (PMID 23889916, 2013).
dermatitis (2 papers, 2023 to 2025). An inflammatory process affecting the skin. "Notably, ACHRG IgM was associated with pneumonitis, anti-cytokeratin 19 IgM with dermatitis, and anti-thyroglobulin IgG with hepatitis." (PMID 38152395, 2023). "Notably, IgM antibodies against ACHRG in pneumonitis, cytokeratin 19 during dermatitis, and IgG antibody against thyroglobulin during hepatitis were significantly elevated during toxicity events compared with 12-week control samples." (PMID 38152395, 2023).
dermatopathy (2 papers, 2021 to 2024). "While VLS symptoms might manifest earlier due to localized skin changes, the immune response against thyroid-specific antigens (like thyroglobulin and thyroid peroxidase) might take longer to develop and become detectable." (PMID 38397367, 2024).
diabetic ketoacidosis (2 papers, 2023). The metabolic condition resulted from uncontrolled diabetes mellitus, in which the shift of acid-base status of the body toward the acid side because of loss of base or retention of acids other than carbonic acid is accompanied by the accumulation of ketone bodies in body tissues and fluids. "Anti-TransGlut IgA: anti- transglutaminase IgA antibody, TPOAb: thyroid peroxidase antibodies, TRAb: thyrotropin receptor antibodies, TgAb: thyroglobulin antibodies, DKA: diabetic ketoacidosis, N/A: information not available, F: Female, M: Male." (PMID 37542216, 2023).
Hepatitis (2 papers, 2018 to 2023). Inflammation of the liver. "When samples obtained at the time of hepatitis were compared with 12-week samples from controls, IgG antibodies against thyroglobulin were higher at the time of toxicity compared to baseline samples among those who developed hepatitis." (PMID 38152395, 2023). "Only the IgG antibody against thyroglobulin was elevated during hepatitis events compared with the 12-week control samples (p=0.008, FDR=0.43) and showed an increase from baseline to the time of toxicity among hepatitis cases (p=0.036, FDR=0.84)." (PMID 38152395, 2023). "In our study cohort, none of the patients who had elevated thyroglobulin IgG antibody levels during hepatitis had thyroid dysfunction at the time of the toxicity event or at the time of their subsequent follow-up." (PMID 38152395, 2023).
hyperthyroxinemia (2 papers, 2022 to 2023). Abnormally elevated thyroxine level in the blood. "This transient inflammatory condition of the thyroid gland is characterized with hyperthyroxinemia, inflammation, pain, and tenderness in the thyroid region, as well as an elevation of serum thyroglobulin concentration." (PMID 35433060, 2022).
inflammatory bowel disease (2 papers, 2023). A spectrum of small and large bowel inflammatory diseases of unknown etiology. "ANA, antinuclear antibodies; fT4, free thyroxine; HLA-B27, human leukocyte antigen B27; IBD, inflammatory bowel disease; JIA, juvenile idiopathic arthritis; RF, rheumatoid factor; SD, standard deviation; TG, thyroglobulin; TPO, thyroid peroxidase; TSH, thyroid stimulating hormone." (PMID 37654906, 2023).
leukocytosis (2 papers, 2025). "Common findings include leukocytosis, elevated CRP and/or ESR, and increased thyroglobulin levels." (PMID 40364264, 2025).
liver cirrhosis (2 papers, 2023 to 2024). "Thyroglobulin and reverse T3 were previously reported to be elevated in liver cirrhosis." (PMID 38125301, 2024).
membranous nephropathy (2 papers, 2022 to 2023). "While membranous nephropathy secondary to Graves’ disease is a rarely reported phenomenon, in a few prior documented cases renal biopsy stained positively for thyroglobulin and TPO, indicating that deposition of such in the kidney was responsible for the secondary membranous nephropathy." (PMID 37477245, 2023).
metastatic carcinoma (2 papers, 2015 to 2020). A carcinoma which has spread from the original site of growth to another anatomic site. "The tumor can simulate a metastatic carcinoma; however, the demonstration of thyroglobulin, TTF1, and PAX8 confirms the thyroid follicular origin." (PMID 32632840, 2020). "Due to its cytoarchitectural pattern, frequent thyroglobulin negativity, and estrogen and progesterone receptor positivity, these tumors can be mistaken for metastatic carcinoma of breast or colorectal origin." (PMID 32632840, 2020).
ovarian tumor (2 papers, 2012 to 2025). "The extremely high levels of Thyroglobulin in local ovarian venous blood compared with that in peripheral blood provide evidence of the production of Thyroglobulin in the ovarian tumor and the normalization of it’s serum levels is related to surgical resection of the tumor." (PMID 22613573, 2012).
Pancytopenia (2 papers, 2012 to 2025). An abnormal reduction in numbers of all blood cell types (red blood cells, white blood cells, and platelets). "The patient was treated with a short-term course of steroids, due to the onset of pancytopenia and borderline antiphospholipid antibodies combined with increased anti-thyroglobulin (anti-TG) titers." (PMID 23227401, 2012).
Pleural effusion (2 papers, 2013 to 2014). The presence of an excessive amount of fluid in the pleural cavity. "Examination of the left pleural effusion by thoracentesis revealed bloody exudate (total protein 4.6g/dL, albumin 2.8g/dL, lactate dehydrogenase 191U/L) with an increase in thyroglobulin (198.9ng/mL)." (PMID 25532447, 2014). "He presented with a 1-month history of progressive dyspnea, and examination of the left pleural effusion revealed a bloody exudate with an increase in thyroglobulin; however, malignant cells in the pleural fluid were negative for thyroglobulin." (PMID 25532447, 2014). "Although the elevated level of thyroglobulin in the pleural fluid might just reflect high serum thyroglobulin levels, it has been reported that elevated pleural fluid thyroglobulin could be a potential biomarker for the diagnosis of metastatic thyroid cancer as a cause of pleural effusion." (PMID 25532447, 2014).
renal carcinoma (2 papers, 2006 to 2017). A carcinoma arising from the epithelium of the renal parenchyma or the renal pelvis. "A positive staining for cytokeratin as well as for vimentin and CD10 in the absence of staining for thyroglobulin, calcitonin and TTF1, observed in smears from both lobes of the thyroid, favored the hypothesis of metastasis from a renal carcinoma." (PMID 17067398, 2006).
syphilis (2 papers, 2023 to 2024). A contagious bacterial infection caused by the spirochete Treponema pallidum. "Serum studies demonstrated normal antinuclear antibodies (ANA), thiamine, anti-Ro, anti-La, thyroid stimulating hormone (TSH), free T3/free T4 (fT3/T4), thyroid peroxidase (TPO) and thyroglobulin (TG) antibodies, syphilis screen, borrelia IgG/IgM antibodies, C-reactive protein (CRP)." (PMID 39628892, 2024).
tuberculosis (2 papers, 2013 to 2014). A chronic, recurrent infection caused by the bacterium Mycobacterium tuberculosis. "Based on cytohistopathology results, thyroglobulin measurement, tuberculosis polymerase chain reaction, and sonographic follow-up, malignant (n = 26) and benign (n = 15) lymph nodes were confirmed." (PMID 23721570, 2013). "Based on the cytohistopathological results (n = 26), thyroglobulin titers (n = 5), tuberculosis polymerase chain reaction (n = 2), and long-term US follow-up (n = 8), 26 malignant and 15 benign lymph nodes were finally determined." (PMID 23721570, 2013).
acromegaly (1 paper, 2024). Acromegaly is an acquired disorder related to excessive production of growth hormone (GH) and characterized by progressive somatic disfigurement (mainly involving the face and extremities) and systemic manifestations. "A thorough study, which included 258 individuals with acromegaly, revealed a 23% prevalence of thyroid peroxidase antibodies (TPOAb) and a 21% prevalence of thyroglobulin antibodies (TgAb)." (PMID 38455769, 2024).
allergic asthma (1 paper, 2022). A asthma with a basis in a pathological type I hypersensitivity reaction. "There is ample evidence suggesting that platelet-specific products, including PF4, β-TG, and platelet microparticles, are elevated in allergic asthma subjects, confirming the presence of platelet activation in allergic asthma." (PMID 35432313, 2022).
angiosarcoma (1 paper, 2012). A malignant tumor arising from the endothelial cells of the blood vessels. "Immunonegativity for thyroglobulin supports a diagnosis of angiosarcoma." (PMID 22553943, 2012).
autoimmune encephalitis (1 paper, 2023). Inflammation of the brain secondary to an immune response triggered by the body itself. "Comprehensive laboratory testing, thyroid peroxidase, thyroglobulin antibodies, and autoimmune encephalitis panel were negative." (PMID 38274926, 2023).
bleeding disorders (1 paper, 2024). "If TG2 inhibitors (small molecule or antibody) are not specific, potential off-target TG inhibition effects can occur, such as parakeratosis from inhibition of TG1, 3, and 5, bleeding disorders following inhibition of Factor XIIIa, and neuron disorders relating to TG6." (PMID 38753630, 2024).
colorectal adenocarcinoma (1 paper, 2023). The most common type of colorectal carcinoma. "The immune markers CK20, CDX2 and Villi protein (Villin) are positively expressed in colorectal adenocarcinoma with absence of thyroglobulin and calcitonin." (PMID 37032350, 2023).
congenital rubella (1 paper, 2023). "Thus, adolescents with congenital rubella were more frequently found to have anti-TPO and anti-TG antibodies and showed a greater proportion of thyroid dysfunction than the control group." (PMID 37293205, 2023).
cystadenoma (1 paper, 2023). A benign or borderline cystic epithelial neoplasm arising from the glandular epithelium. "The solid adenoma was positive for thyroglobulin in immunohistochemistry staining, whereas the cystadenomas stained positive for both thyroglobulin and calcitonin." (PMID 39149141, 2023).
cystic fibrosis (1 paper, 2021). Autosomal recessive disorder caused by pathogenic variants in the CFTR gene (cystic fibrosis transmembrane conductance regulator), which encodes a chloride and bicarbonate channel expressed in epithelial cells, and follow the diagnosis criteria. "Internal positive control glycoproteins for O6 binding on this microarray included bovine and human thyroglobulin as well as human respiratory mucin from both nondiseased (ND) and Cystic Fibrosis patients." (PMID 34083726, 2021).
cystinosis (1 paper, 2016). Cystinosis is a metabolic disease characterized by an accumulation of cystine inside the lysosomes, causing damage in different organs and tissues, particularly in the kidneys and eyes. "Earlier thyroid changes affecting thyroglobulin synthesis and iodo-thyroglobulin processing might be responsible for subclinical hypothyroidism with TSH elevation and normal T3 and T4 plasma concentrations, as it has been shown in a mouse model of cystinosis." (PMID 27102039, 2016).
euthyroid goitre (1 paper, 2024). "FL was diagnosed in one female patient aged 54 years old, with a history of euthyroid goitre, and a high level of anti-thyroglobulin antibodies." (PMID 38541203, 2024).
fibrosis (1 paper, 2015). the formation of excess fibrous connective tissue in an organ or tissue in a reparative or reactive process. "Fibrosis does not progress during the early stages of the immune response, which may explain why serum titers of anti-thyroglobulin antibodies were not correlated with SWV." (PMID 26257979, 2015).
glomerulopathies (1 paper, 2021). "The most likely mechanisms of coexistence of AITD with glomerulopathies are the glomerular deposition of immune complexes of thyroglobulin and autoantibodies, as well as impaired immune tolerance to megalin (a glycoprotein regulated by TSH, located on the thyrocyte apical surface)." (PMID 34183993, 2021).
invasive carcinoma (1 paper, 2017). A carcinoma that is not confined to the epithelium, and has spread to the surrounding stroma. "A vertebral biopsy was performed finding an invasive carcinoma, CK7+/CK20+, TTF1-, PSA-, Thyroglobulin- and GATA3+." (PMID 28494780, 2017).
leiomyosarcoma (1 paper, 2016). An uncommon, aggressive malignant smooth muscle neoplasm, usually occurring in post-menopausal women. "In the cases presented, the fact that negative staining of the tumor with thyroglobulin, TTF-1, and keratin, and that positive staining was observed with vimentin and actin in the first case specimen, led to the immunohistopathological diagnosis of leiomyosarcoma." (PMID 27080750, 2016).
mucinous cystadenoma (1 paper, 2014). A benign or low malignant potential cystic epithelial neoplasm composed of cells which contain intracytoplasmic mucin. "Both mucinous cystadenoma as well as struma present with locules containing hyperintense content on T1, representing the mucinous material in the first and thyroglobulin in the latter." (PMID 24357453, 2014).
myelitis (1 paper, 2014). An inflammatory process affecting the spinal cord. "Furthermore, levels of TSH, TG-Ab, TPO-Ab in patients with myelitis were significantly different to patients without myelitis." (PMID 25093326, 2014).
oncocytic carcinoma of the thyroid (1 paper, 2006). "Metastatic oncocytic carcinoma of the thyroid (Hürthle cell carcinoma) can be diagnosed because of the immunohistochemical expression of thyroglobulin." (PMID 16923179, 2006).
peritoneal disease (1 paper, 2025). "Thyroglobulin levels may remain undetectable even in recurrent peritoneal disease, which highlights the limitations of relying solely on biochemical surveillance." (PMID 40922876, 2025).
Renal cyst (1 paper, 2016). A fluid filled sac in the kidney. "We found increased I-131 WBS uptake at the site of a renal cyst in a patient who had no other evidence of metastatic thyroid cancer, and the level of thyroglobulin was not elevated." (PMID 26977418, 2016).
salivary carcinoma (1 paper, 2015). "According to HE and immunohistochemistry, it was diagnosed as salivary carcinoma because of positive expression of α-SMA, negative expression of cytokeratin 7 and thyroglobulin." (PMID 25868857, 2015).
SAPHO syndrome (1 paper, 2021). SAPHO syndrome (acronym for Synovitis, Acne, Pustulosis, Hyperostosis and Osteitis) is an auto-inflammatory disease, mainly characterized by the association of neutrophilic cutaneous involvement and chronic osteomyelitis. "From the perspective of autoimmunity, several previous studies have assessed anti-thyroid peroxidase (TPO), anti-thyroglobulin (Tg), and anti-nuclear antibodies in patients with SAPHO syndrome." (PMID 33392854, 2021).
thrombotic disease (1 paper, 2025). The formation of a blood clot in the lumen of a vessel or heart chamber; causes include coagulation disorders and vascular endothelial injury. "Of note, thyroglobulin elevation also occurred in those with thrombotic disease without distant metastases." (PMID 40070593, 2025).
thymoma (1 paper, 2016). A neoplasm arising from the epithelial cells of the thymus. "In thymoma‐MG, anti‐TPO and anti‐TG antibodies were present in 11.1% females and 8.3% males (p = ns)." (PMID 27781146, 2016).
thyroid angiosarcomas (1 paper, 2024). "By immunohistochemistry, thyroid angiosarcomas are strongly and diffusely positive for pan-endothelial markers, i.e., CD31, CD34, FLI-1 and ERG, but lack expression of thyroid-related immunomarkers including thyroglobulin, TTF1 and PAX8." (PMID 39422760, 2024).
urinary tract infection (1 paper, 2024). "His second post-transplant course in 2017 was complicated by antibody-mediated rejection, recurrent urinary tract infections, and an episode of cell-mediated rejection, which was treated with both corticosteroids and thyroglobulin." (PMID 39866980, 2024).